TGFB1 (transforming growth factor beta 1)
Diseases named in the same sentence as TGFB1 in open-access papers (continued):
Sharing a sentence is not in itself a finding about the gene and the disease.
asthma (continued). "Our results demonstrated that at basal levels, LF isolated from asthma patients (DHLF) exhibit higher expression of NOX4 and α-SMA compared to fibroblasts from normal (NHLF) subjects, which were significantly increased in response to TGFβ1." (PMID 32555397, 2020). "Exposure to rOPN could induce the expression of Tgfβ1 and the release of TGF-β1, IL-5, IL-13, and phosphorylated Smad3 in a mouse model of virus-induced asthma exacerbation." (PMID 32009132, 2020). "For example, in an asthma mice model, TRPV4 activation in the membrane promotes an increase in transforming growth factor- beta 1 (TGF-β1) through a signaling pathway involving PI3K and leads to stimulation of the myocardin-related transcription factor A (MRTF-A), which depends on Rho/myocardin." (PMID 32481620, 2020). "Of note, KCa3.1 blockade reduced several aspects of TGFβ1-dependent EMT, suggesting that KCa3.1 blockers may reduce airway wall fibrosis in asthma and COPD." (PMID 26689552, 2015). "ASM cells from people with and without asthma were stimulated with TGFβ1 (1 ng/ml) with or without budesonide (10−8 M) and formoterol (10−10 and 10−8 M), and fibronectin expression and IL-6 release were measured by ELISA." (PMID 22500185, 2012). "Unfortunately, the contribution of mast cells to the upregulation of TGFβ1 expression in asthma is not clear either." (PMID 17892594, 2007). "In all studies documenting an absence of regulation of TGFβ1 expression in asthma, lung specimens had been taken at baseline, i.e. in a remission period where no sign of exacerbation was present or without prior experimentally-induced bronchoprovocation." (PMID 17892594, 2007). "None of the well-defined asthma/inflammatory genes (Il1b, Il4, Il10, Il13, Il6, Tnfa, Infg, Tgfb1) are differentially expressed, although they connect many of the genes that are." (PMID 18087596, 2007). "In summary, this study demonstrates considerable changes in circulating immune cell subset abundance during an acute asthma exacerbation, which is accompanied by differential gene expression and modulation of signalling networks, some of which are driven by LPS/LBP, glucocorticoids and TGFB1." (PMID 37438758, 2023). "According to these analyses, IL-1R2, BAX, and TGFB1 were of particular interest due their “High” relationship level with allergic asthma and “Moderate” or weaker relationship value with allergy or nonallergic asthma." (PMID 33936056, 2021). "However, 6 studies performed with human tissues have shown no regulation of TGFβ1 expression in asthma." (PMID 17892594, 2007). "Finally, the different points of regulation that can affect the amplitude of the TGFβ1 response are briefly revised and the possibility that TGFβ1 is disregulated at another level in asthma, rather than simply in its expression, is highlighted." (PMID 17892594, 2007). "Further, TGFβ1 was identified as a putative driver of the molecular changes specific to IRF7lo viral asthma exacerbations, and recent transcriptomic analyses of nasal epithelium confirms a SMAD3-centered molecular signature associated with both viral and non-viral asthma exacerbations in children." (PMID 34367159, 2021).
diabetic nephropathy (560 papers, 2001 to 2026). "Evidence from experimental animal and in vitro studies also recapitulated the pathogenic role of TGFβ1 in diabetic nephropathy." (PMID 36430743, 2022). "Patients with morbid obesity and diabetic nephropathy showed a high expression level of TGFβ1, and an enhanced level of TGFβ1 was reported as a risk factor for type-2 DM." (PMID 36430743, 2022). "The loss of podocytes is a key aspect of diabetic nephropathy and a variety of factors have been implicated, most notably TGFβ1." (PMID 24795631, 2014). "Transforming growth factor beta (TGFβ1) is a multifunctional cytokine implicated in the pathogenesis of many forms of progressive renal disease, including diabetic nephropathy, by promoting renal hypertrophy and the accumulation of extracellular matrix." (PMID 17319955, 2007). "The TGFB1: +869T>C SNP has been associated with diabetic nephropathy in a Chinese population with type 2 diabetes, however our results do not support this finding for nephropathy in type 1 diabetes." (PMID 17319955, 2007). "We have assessed five SNPs, suggested to play a role in TGFβ1 expression levels through their impact on regulatory regions of TGFB1, for association with diabetic nephropathy." (PMID 17319955, 2007). "We investigated the role of five known single nucleotide polymorphisms (SNPs) in the TGFB1 gene for their association with diabetic nephropathy in an Irish, type 1 diabetic case (n = 272) control (n = 367) collection." (PMID 17319955, 2007). "This is in contrast to a larger study in UK Caucasians where a significant association (p = 0.027) was identified between TGFB1: +869T>C and diabetic nephropathy." (PMID 17319955, 2007). "Although experimental evidence suggests TGFβ1 blockade may be an important therapeutic target we were unable to identify any association between TGFB1 gene variants and diabetic nephropathy." (PMID 17319955, 2007). "We have investigated the role of five known single nucleotide polymorphisms, which may influence TGFB1 gene expression (TGFB1: -800G>A, -509C>T, +72InsC, +869T>C, +915G>C) for their association with diabetic nephropathy." (PMID 17319955, 2007). "But this enzyme also stimulates the gene expression of TGFβ1 (transforming growth factor beta 1), a cytokine involved in the development of diabetic nephropathy." (PMID 41226982, 2025). "Inflammation is of special importance in pathologies such as diabetic kidney disease, hence the extent of response to IL-1β, diabetic milieu and TGFβ1 stimulation was deemed interesting to explore." (PMID 41023975, 2025). "A recent study, in the context of diabetic nephropathy, suggested that chronic exposure to glucose-evoked TGFβ1 induced an increase in Cx43 expression, consistent with changes observed in renal tubular epithelia from patients." (PMID 39707203, 2024). "Of the various cytokines playing a role in the pathogenesis of diabetic nephropathy, transforming growth factor beta-1 (TGF-β1) is an important one." (PMID 37842382, 2023). "Apigenin regulated MAPK-NF-κB-TNF-α and transforming growth factor-beta-1 (TGF-β1)-MAPK-fibronectin signalling in STZ-induced diabetic nephropathy." (PMID 35566252, 2022). "Previous human studies have shown systemic levels of TGFβ1 increase in type-1 and type-2 DM, obesity with insulin resistance, and diabetic nephropathy." (PMID 36430743, 2022). "Several cases of evidence have proved the critical role that TGFβ1 plays in the pathogenesis of diabetic nephropathy." (PMID 36430743, 2022). "Patients with diabetic nephropathy also show high urinary levels of TGFβ1, and mice with the glomerulus-specific overexpression of human TGFβ1 develop chronic kidney disease and renal failure." (PMID 36430743, 2022). "miR-154-5p regulates the TGFβ1/Smads pathway through Smurf1 ubiquitination and promotes the fibrosis process of diabetic kidney disease." (PMID 35126820, 2022).
diabetic nephropathy (continued). "The circulating levels of TGFβ1 are significantly increased in diabetic nephropathy and are significantly correlated with the severity of renal dysfunction." (PMID 36430743, 2022). "Yet, targeting the latent form of TGFβ1 instead of the active one holds promise for the treatment of diabetic kidney disease in the future." (PMID 34319011, 2021). "Expression of transforming growth factor beta 1 (TGF-β1) is upregulated in diabetic nephropathy and in cultured podocytes exposed to high glucose." (PMID 32708597, 2020). "It is conceivable that in the context of TGFβ1 overproduction in the glomerulus, e.g., diabetic nephropathy, TGFβ1 activates Rac1 in podocytes, ultimately leading to podocyte loss and glomerulosclerosis." (PMID 29415466, 2018). "Conversely, lack of type VIII collagen conferred renoprotection in a mouse model of diabetic nephropathy, modulated TGFβ1 signalling and resulted in abnormal development of the anterior segment of the eye, including the cornea." (PMID 28331057, 2017). "NCF1, OSM, SMAD1 and TGFB1 provide protection against diabetic nephropathy, SYVM1 and TXNIP protect against diabetic retinopathy and BDNF in ameliorating the diabetic neuropathy." (PMID 28761062, 2017). "We then sought to identify miRNAs that were differentially regulated in TGFβ1- treated (diabetic nephropathy condition) NRK-52E cells." (PMID 27874055, 2016). "TSP1-mediated TGFβ1/Smads signaling contributes to target-organ damage in animals with diabetic nephropathy and diabetic cardiomyopathy." (PMID 25884585, 2015). "The inhibition of AR activity and TGFβ-1 expression has an important role in improving diabetic nephropathy." (PMID 25849026, 2015). "Tranilast, a membrane-stabilizing agent of mast cells used for treating bronchial asthma, suppresses collagen synthesis in early and advanced diabetic nephropathy by interfering with the actions of TGFβ1." (PMID 25884585, 2015). "A recent study has shown that (Pro)renin receptor (PRR) promoted the progression of diabetic nephropathy through enhanced TGFβ1 CCN2 signaling cascade, which was evidenced by administering PRR blockade in vivo and in vitro." (PMID 26421309, 2015). "Critical components of the diabetic milieu, glucose, and advanced glycation end-products (AGEs), induce TGFβ1 expression in human diabetic nephropathy as well as in mesangial cells and proximal tubule epithelial cells in culture." (PMID 24795631, 2014). "The role of TGFβ1 in pathogenesis of diabetic nephropathy is pathologic tissue fibrosis leading to organ failure." (PMID 24710116, 2014). "In a rat model, sirolimus lowered expression and activity of glomerular transforming growth factor-beta 1/2 and vascular endothelial growth factor, all of which are considered central cytokines in the pathogenesis of diabetic nephropathy." (PMID 23762090, 2013). "High glucose in itself increases TGFβ1, a prominent profibrotic cytokine responsible for laying down extracellular matrix in diabetic nephropathy." (PMID 23390498, 2013). "The aim of this study was to investigate the role of Nox4 inhibition on TGFβ1-induced fibrotic responses in proximal tubular cells and in a mouse model of diabetic nephropathy." (PMID 23991195, 2013). "Because TGFB1 is a key mediator of ECM accumulation in diabetic nephropathy, and PAI-1 inhibits ECM turnover, we also examined the effect of glucose on expression of these genes." (PMID 21526116, 2011). "Delineation of the relationship between TGFB1 and PVT1 therefore represents a critical component toward understanding the molecular mechanisms underlying the regulation of ECM in diabetic nephropathy." (PMID 21526116, 2011). "In summary, we investigated if putatively functional variants in three genes, TGFB1, TGFBR1 and TGFBR2, contribute to genetic susceptibility to diabetic nephropathy in type 1 diabetes." (PMID 17319955, 2007). "Transforming growth factor (TGFβ1) is a crucial mediator in the pathogenesis of diabetic nephropathy." (PMID 17319955, 2007).
diabetic nephropathy (continued). "Moreover, polydatin treatment significantly mitigated the AGEs-induced overexpression of transforming growth factor-beta 1 (TGF-β1) and fibronectin, both of which are pivotal in the fibrotic processes associated with diabetic nephropathy." (PMID 40958722, 2025). "Additionally, the role of TGFβ1 in diabetic nephropathy is well described where TGFβ1 plays a role as a prognostic marker and an active player in disease progression." (PMID 35740425, 2022). "Transforming growth factor beta 1 (TGFβ1) is a major driver of fibrosis in diabetic kidney disease." (PMID 26379674, 2015). "CTGF is an established effector of TGFβ1 driven responses in diabetic nephropathy." (PMID 25327961, 2014). "TGFβ1 holds a major role in the development of diabetic nephropathy." (PMID 24795631, 2014). "Moreover, the podocytopaenia observed in diabetic nephropathy is due to podocyte apoptosis in which TGFβ1 is crucially culpable where it induces apoptosis of cultured murine podocytes." (PMID 24795631, 2014). "For instance, in rodent models of diabetic kidney disease, oxidative stress has been associated with increased levels of nuclear factor kappa B (NF-kB), tumor necrosis factor-alpha (TNF-α), and transforming growth factor beta-1 (TGF-β1), while antioxidant systems are impaired." (PMID 39456409, 2024). "Saponins could also be involved in various therapeutic pharmacological activities in diabetic conditions, including inhibition of AGE formation and oxidative stress, as well as transformation of growth factor β1 (TGFβ1), thereby preventing the development of diabetic nephropathy." (PMID 34073543, 2021). "Han used machine learning to obtain two diagnostic markers of protein kinase cAMP-dependent type II regulatory subunit beta and transforming growth factor beta 1 (PRKAR2B and TGFBI, respectively) in glomerular injury in diabetic nephropathy." (PMID 36960398, 2023). "The aim of this research was to assess the effects of Liraglutide in a cell culture model of diabetic nephropathy on cell viability, antioxidant (GSH) and transforming growth factor beta 1 (TGF- β1) levels and extracellular matrix (ECM) expression." (PMID 35723295, 2022). "There is considerable evidence supporting the role of TGFB1, TGFBR1 and TGFBR2 genes in the development of diabetic nephropathy." (PMID 17319955, 2007). "The activity of TGFβ1 is facilitated by the action of type 1 and type 2 receptors, with both receptor genes (TGFBR1 and TGFBR2) shown to be upregulated in diabetic kidney disease." (PMID 17319955, 2007). "Using TNF as predictive marker and TGFB1 and EDN1 as monitoring markers might be a valuable strategy finding the subset of diabetic nephropathy patients benefitting the most from tacrolimus treatment." (PMID 28060893, 2017). "Our results suggest common variants in TGFB1, TGFBR1 and TGFBR2 genes do not strongly influence genetic susceptibility to diabetic nephropathy in an Irish Caucasian population." (PMID 17319955, 2007). "To demonstrate this hypothesis, we compared the development of insulin resistance, DM, and the progression of diabetic nephropathy between diabetic and non-diabetic transgenic (TG) mice overexpressing human TGFβ1 in the kidneys and wild-type (WT) mice." (PMID 36430743, 2022). "Since Nox4 is the major source of ROS in the kidneys during the early stages of diabetic nephropathy and in order to confirm the effect of TGFβ1 on ROS production, the levels of SOD1, which constitutes the first line of defence against ROS were determined following TGFβ1 treatment." (PMID 23991195, 2013).
ovarian carcinoma (554 papers, 2006 to 2026). A malignant neoplasm originating from the surface ovarian epithelium. "Ovarian cancer-derived exosomes induced fibroblasts to cancer-associated fibroblasts (CAFs) and promoted the production of transforming growth factor 1 (TGFβ1) and activation of somatic mutations in the Mothers Against Decapentaplegic Homolog (SMAD) signaling." (PMID 37497408, 2023). "TGFβ1 is upregulated in ovarian cancer tissues and is associated with tumor progression, chemotherapy resistance and a poor prognosis." (PMID 34621667, 2021). "And CCAT1 knockdown decreased cell migration, invasion and EMT-associated markers expression of ovarian cancer cells treated with TGFβ1." (PMID 30250403, 2018). "To further investigate the mechanism underlying TGFβ1-induced invasion and migration of ovarian cancer cells regulated by CCAT1, we examined the expression of EMT-associated genes in control and sh-CCAT1 ovarian cells." (PMID 30250403, 2018). "Taken together, these results revealed that CCAT1 loss led to remarkably attenuated EMT of ovarian cancer cells treated with TGFβ1." (PMID 30250403, 2018). "This is intriguing in light of previous studies reporting the presence of TNFα and TGFβ1 in the ascites of the vast majority of ovarian cancer patients and their association with disease progression." (PMID 27659538, 2016). "Gene-based analysis identified SMAD6 and TGFB1 (P<0.05 for all SNPs examined in each gene using the dominant or additive model) as genes associated with ovarian cancer risk." (PMID 21984931, 2011). "Although several DUSP proteins have been associated with malignant properties of ovarian cancer cells, whether TGFβ1 causes changes in DUSP expressions is currently unknown." (PMID 37476896, 2023). "In ovarian cancer, TGFβ1 induction has been shown to be a hallmark of EMT." (PMID 36463238, 2022). "In ovarian cancers, for example, there is an increased expression of the mesenchymal spliced variant CD44s (standard) and a concurrent decrease in the epithelial variant (CD44v); during TGFβ1-induced EMT, there is a predominance of CD44s." (PMID 34831291, 2021). "In addition, we preliminarily studied the mechanisms underlying the effect of CFG in suppressing ovarian cancer cell proliferation as well as TGFβ1-induced EMT in vitro." (PMID 28036353, 2016). "In ovarian cancer tissues and ascitic fluid, Tfr cells have been found to infiltrate and express high levels of TGFB1 and IL-10." (PMID 40703514, 2025). "The expression of DUSP13 was reduced after epithelial-mesenchymal transition of the ovarian cancer cell line triggered by TGFβ1." (PMID 39062022, 2024). "This was indicative of the importance of the positive feedback loop between SMYD3/ITGB6/TGFβ1 in enhancing the invasion and adhesion of ovarian cancer spheroids as well as cell–cell communication in these models." (PMID 38254117, 2024). "For instance, FAM83D promotes cell invasion and chemo-resistance by regulating AKT/mTOR and TGFβ1-pSMAD2/3 signaling in lung and ovarian cancer." (PMID 38454442, 2024). "In ovarian cancer progress and metastasis, TGFβ1 is known to induce EMT, which is accompanied by increased MAPK activity." (PMID 37476896, 2023). "DUSP proteins are recognized as key regulators of MAPK proteins which play essential roles in TGFβ1-induced EMT, which is associated with the acquisition and maintenance of malignant features and chemotherapy resistance in ovarian cancer." (PMID 37476896, 2023). "The expression levels of carboplatin resistance-associated proteins, AKR1B1, ITGAV, TGFβ1 and G6PD, in platinum resistant and relapsed human ovarian cancer samples are consistent with our observations in vitro data on control and carboplatin-resistant cells." (PMID 36463238, 2022). "Our results showed that platelets increased PD-L1 expression in ovarian cancer cells, partially through direct binding and activation of NF-κB signaling and partially through secreted TGFβ1 activating TGFβR1/Smad signaling." (PMID 35626102, 2022).